ECD (ecdysoneless cell cycle regulator)
Description:
May be involved transcriptional regulation. In vitro has intrinsic transactivation activity enhanced by EP300. May be a transcriptional activator required for the expression of glycolytic genes. Involved in regulation of cell cycle progression. Proposed to disrupt Rb-E2F binding leading to transcriptional activation of E2F proteins. The cell cycle -regulating function may depend on its RUVBL1-mediated association with the R2TP complex. May play a role in regulation of pre-mRNA splicing. Participates together with DDX39A in mRNA nuclear export.
Synonyms: hSGT1; GCR2; SGT1
Tractability: PROTAC: ubiquitination databases record sites on it; its protein half-life has been measured.
Gene: Protein-coding gene on chromosome 10 (73,130,155 to 73,169,055, reverse strand). Ensembl gene ENSG00000122882.
Subcellular location: Cytoplasm; Nucleus
Subcellular location (Human Protein Atlas): Cytosol; Nucleoplasm
Gene Ontology:
Molecular function: histone acetyltransferase binding; protein binding
Biological process: positive regulation of transcription by RNA polymerase II
Cellular component: cytoplasm; cytosol; nucleoplasm; nucleus
Genetic constraint (gnomAD): Loss-of-function variants: 47 observed, 67.48 expected, observed/expected ratio (o/e) 0.7, 90% interval 0.55 to 0.89. The upper end of that interval is the gene's LOEUF score, 0.89, which puts it in group 3 of 6, group 1 being the genes least tolerant of losing a copy. Missense variants: 630 observed, 723.12 expected, observed/expected ratio (o/e) 0.87, 90% interval 0.81 to 0.93. Synonymous variants: 214 observed, 259.31 expected, observed/expected ratio (o/e) 0.83, 90% interval 0.74 to 0.92.
Homologues: Orthologues: chimpanzee ECD (99% identical), macaque ECD (95% identical), rabbit ECD (88% identical), dog ECD (87% identical), pig ECD (86% identical), guinea pig ECD (84% identical), rat Ecd (80% identical), mouse Ecd (78% identical), tropical clawed frog ecd (61% identical), zebrafish ecd (51% identical), Drosophila melanogaster ecd (33% identical), Caenorhabditis elegans F19C6.2 (14% identical).
Diseases named in the same sentence as ECD in open-access papers:
ECD is named in the same sentence as 20 diseases in open-access papers, as found by Europe PMC text mining. Sharing a sentence is not in itself a finding about the gene and the disease. The quoted sentences say what the papers report.
pancreatic cancer (6 papers, 2016 to 2025). "Recently, ECD over-expression has been closely associated with a poor prognosis in pancreatic cancer." (PMID 26498357, 2017). "It was further shown that the GLUT4 transcriptional regulator, GLUT4 enhancer factor, and protein expression are down-regulated after the KD of ECD in pancreatic cancer cells." (PMID 41308033, 2025). "Others have showed that ECD knockdown reduced cell growth, proliferation and tumorigenicity in vivo while affecting glucose uptake by pancreatic cancer cells and reduced phosphorylation of Akt." (PMID 34680332, 2021). "Further studies demonstrated ECD is overexpressed in breast and pancreatic cancers and its overexpression correlates with poor patient survival." (PMID 28492064, 2016). "Additionally, overexpression of ECD was described in different types of tumors such as breast and pancreatic cancer and correlated with poor prognosis and shorter survival of patients." (PMID 34680332, 2021). "In accordance with previously published studies in gastric, prostatic and pancreatic cancer, we show here that overexpression of ECD-Sema5A increased in vitro cell migration and invasion properties of melanoma cells, with a concomitant activation of the Akt/ERK pathways." (PMID 30454024, 2018). "Additionally, knockdown of ECD reduces pancreatic cancer cell growth and tumorigenicity." (PMID 26498357, 2017).
breast carcinoma (3 papers, 2021 to 2025). "In breast cancer, ECD protein is overexpressed and its overexpression is correlated with shorter survival, particularly in ErbB2-overexpressing patients." (PMID 33941617, 2021). "We have shown that ECD overexpression in breast cancer patients correlates with poor prognosis and shorter survival, especially in the ErbB2+ breast cancer subtype." (PMID 33941617, 2021). "Taken together, our studies reveal a novel role of ECD, an independent prognostic marker in breast cancer patients, as an essential and important component of the mRNA export machinery." (PMID 33941617, 2021). "ECD mRNA is overexpressed in breast cancer patients, and its mRNA overexpression serves as an independent prognostic marker that predicts survival in breast cancer patients." (PMID 33941617, 2021). "Using ErbB2-overexpressing breast cancer cell lines, we implicate ECD as a regulator of ErbB2 mRNA export and stability to promote ErbB2-driven oncogenic traits." (PMID 33941617, 2021). "We have previously shown that ECD protein is overexpressed in ErbB2+ breast cancers (BC)." (PMID 33941617, 2021). "We previously showed that ECD protein is overexpressed in ErbB2+ breast cancers (BC)." (PMID 33941617, 2021). "ECD protein is overexpressed in a significant subset of breast cancers and is also upregulated in other cancers (38, –, 41), and its overexpression correlates with poor prognosis and short survival in ErbB2-overexpressing breast cancers." (PMID 33941617, 2021). "Given our previous findings that ECD protein is overexpressed in cancers, including breast cancers (BC), we wished to analyze if overexpression of ECD protein is due to increased mRNA levels and if mRNA export function of ECD relates to its oncogenic function in breast cancer cells." (PMID 33941617, 2021).
gastric cancer (3 papers, 2017 to 2025). A primary or metastatic malignant neoplasm involving the stomach. "In gastric cancer (GC), ECD overexpression is associated with poor prognosis." (PMID 41308033, 2025). "Collectively, our data indicates that ACK1 promotes gastric cancer growth and survival mainly by up-regulating ECD expression." (PMID 26498357, 2017). "Here, we found that ECD is frequently overexpressed in gastric cancer (GC), especially in metastatic GC, and is correlated with poor clinical outcomes in GC patients." (PMID 29706618, 2018). "Furthermore, ECD expression levels were investigated in gastric carcinoma." (PMID 26498357, 2017).
gastric intestinal adenocarcinoma (2 papers, 2017 to 2018). "ECD mRNA levels were higher in gastric intestinal-type adenocarcinoma and gastric adenocarcinoma tissues than in gastric mucosal tissues, indicating that ECD expression is upregulated in GC." (PMID 29706618, 2018). "Higher ECD mRNA levels were observed in diffuse gastric adenocarcinoma or gastric intestinal adenocarcinoma compared to gastric mucosa tissues in the Chen and Derrico gastric datasets, respectively." (PMID 26498357, 2017).
gastric tumor (2 papers, 2021). "The importance of understanding the mechanism of how ECD functions is further highlighted by studies by us and others that have demonstrated ECD overexpression in several human cancers, such as those of pancreas, breast, and gastric tumors (38, –, 41)." (PMID 33941617, 2021).
cardioembolic stroke (1 paper, 2019). "CAV1, SURF1, PLEKHH2, ECD, BNIP1, CAV2 are found to be associated with cardioembolic stroke and Small vessel stroke in Europeans." (PMID 32038707, 2019).
meningioma (1 paper, 2023). A generally slow growing tumor attached to the dura mater. "Six antigens were exclusively found in the immunopeptidome of WHO grade I meningiomas (CAPN14, KIR2DS4, TMM44, ECD, CD86, and RFWD3), whereas WHO grade I and III meningiomas showed only one antigen in common (KLC2)." (PMID 37368072, 2023).
osteosarcoma (1 paper, 2018). A usually aggressive malignant bone-forming mesenchymal neoplasm, predominantly affecting adolescents and young adults. "Our results demonstrate different patterns of BALP and ECD/HER-2 proteins in patients with osteosarcoma during clinical treatment." (PMID 29641422, 2018). "Serum levels of BALP and ECD/HER-2 in osteosarcoma patients with remission or progression of disease after therapy." (PMID 29641422, 2018). "Our results demonstrate the different pattern of BALP and ECD/HER-2 proteins during clinical treatment in patients with osteosarcoma." (PMID 29641422, 2018). "Serum levels of BALP and ECD/HER-2 in osteosarcoma patients depending on the metastasis status at initial diagnosis." (PMID 29641422, 2018). "The values of BALP and ECD/HER-2 proteins were higher (p<0.01; p<0.05, respectively) in patients with osteosarcoma at the time of diagnosis compared with the control group." (PMID 29641422, 2018).
triple-negative breast carcinoma (1 paper, 2021). An invasive breast carcinoma which is negative for expression of estrogen receptor (ER), progesterone receptor (PR), and human epidermal growth factor receptor 2 (HER2). "In the METABRIC data set, ECD overexpression also correlated with poor patient survival in triple-negative breast cancer (TNBC)." (PMID 33941617, 2021).
tumor (12 papers, 1995 to 2026). "Considering the important role of ECD in cell growth, a targeted inhibitor that can find its specific site would be a better solution to the infinite proliferation of tumor cells." (PMID 41308033, 2025). "Ecdysoneless (ECD) has been studied as a tumor-promoting gene in PDAC that activates pAkt, a molecule that regulates glycolysis in tumor cells and enhances the expression of solute carrier family 2 (facilitated glucose transporter), member 4 (GLUT4) to strengthen glycolysis." (PMID 35406597, 2022). "The silencing of ECD did not further enhance the effects of ACK1 knockdown on G2/M arrest and apoptosis because ECD expression has been significantly lower when ACK1 was silenced, suggesting that ECD is an important downstream effector of ACK1 in the regulation of tumor growth and cellular survival." (PMID 26498357, 2017). "Overexpression of ECD in cervical, head, and neck squamous cell carcinoma (HNSCC) cell lines and tumor tissues indicates shorter survival of patients." (PMID 41308033, 2025). "Thus, to specifically determine if Gr1−/lowCD11b−/low myeloid cells could cross‐present Ag to provoke a T cell response, we sorted splenic Gr1−/lowCD11b−/low myeloid cells and pulsed them with recombinant Neu ECD protein, followed by a culturing period with tumor‐sensitized T cells." (PMID 29985529, 2018).
cancer (4 papers, 2017 to 2022). A tumor composed of atypical neoplastic, often pleomorphic cells that invade other tissues. "ECD mutations were found to be associated with shorter survival in renal, ovarian and pan-cancer studies (3 studies)." (PMID 35444210, 2022). "ECD-dependent ErbB2 mRNA export is functionally relevant in the context of overexpressed ECD in cancer cells, which is supported by our observations that KD of ECD dramatically reduced the oncogenic traits." (PMID 33941617, 2021). "Given the importance of ECD in the cell cycle, cell survival, and embryogenesis and its overexpression across human cancers, our findings provide a new mechanism that could help understand the physiological and pathological roles of ECD." (PMID 33941617, 2021). "The human ortholog of the Drosophila ecdysoneless gene (ECD) is required for embryonic development and cell-cycle progression; however, its role in cancer progression and metastasis remains unclear." (PMID 29706618, 2018). "ECD, IL4R and WDR82 are protein coding genes, not commonly known to be associated with cancer risk or prognosis." (PMID 35444210, 2022). "Collectively, our findings indicate that ECD promotes cancer invasion and metastasis by preventing E3 ligase ZFP91-mediated hnRNP F ubiquitination and degradation, suggesting that ECD may be a marker for poor prognosis and a potential therapeutic target for GC patients." (PMID 29706618, 2018). "Given that the PERK arm of the UPR is also activated in cancer and that both ECD and GRP78 are overexpressed in cancer (69, 70, 76, –, 81), we suggest that ECD overexpression may play a similar role to mitigate the negative consequences of elevated PERK signaling found in cancer." (PMID 28652267, 2017).
infection (1 paper, 2025). The state of being infected such as from the introduction of a foreign agent such as serum, vaccine, antigenic substance or organism. "In the infection growth assay, the growth curves of T4-infecting E. coli suggest the existence of a defense system, with plasmid-borne EcD granting the E. coli immunity against T4 infection." (PMID 40498078, 2025).
ECD also shares sentences with these, for which no sentence is quoted: colorectal tumours (1 paper); diabetes (1); diffuse gastric adenocarcinoma (1); gastric adenocarcinoma (1); melanoma (1); small vessel stroke (1); thyroid cancer (1); thyroid tumor (1).